CCL20 (C-C motif chemokine ligand 20)
Diseases named in the same sentence as CCL20 in open-access papers (continued):
Sharing a sentence is not in itself a finding about the gene and the disease.
tumor (627 papers, 2005 to 2026). "These KRT15high stem-like tumor cells specifically secreted CCL20, which was related to the infiltration of TLS-associated immune cells in HPV+HNSCC." (PMID 41462011, 2025). "CCL20, a chemokine best known to induce leucocyte migration in response to pathological and inflammatory conditions, has been implicated in tumor proliferation, angiogenesis, metastasis, immunosuppression, and therapeutic resistance." (PMID 39985603, 2025). "Liver cancer cells recruit tumor‐associated macrophages (TAMs) by secreting specific factors, such as CCL20, which reshapes the pulmonary immune microenvironment and suppresses the anti‐tumor immune response." (PMID 40387186, 2025). "P.g. also manipulates inflammatory signaling in SCC-25 cells by activating NF-κB and MAPK pathways, driving tumor-associated inflammation and metastasis via upregulation of CCL20, TNFAIP6, CXCL8, TNFAIP3, TRAF5, CYP1A1, and NOD2 gene expression." (PMID 40924302, 2025). "High expression of CCL20 in tumor cells is associated with endothelial migration, tube formation, and angiogenesis." (PMID 39985603, 2025). "Our study demonstrates for the first time that high VDR expression in PAAD cells promotes CCL20 transcription and release, inducing functional changes in tumor-associated macrophages." (PMID 38600588, 2024). "In the tumor microenvironment, CCL20 can cause the exhaustion of CCR6+ tumor-infiltrating T cells and concomitantly support the growth and metastasis of CCR6+ tumor cells." (PMID 38472446, 2024). "In CRC, CCL20 has been found to be dysregulated, with elevated levels observed in tumour tissues and associated with cancer progression and poor clinical outcomes." (PMID 38809918, 2024). "We found that tumor tissues with high expression of RANK or CCL20 were strongly associated with enhanced FOXP3 expression." (PMID 38902257, 2024). "PPARδ increased Ccl20 level to chemoattract Ccr6+ immunosuppressive cells, including tumor-associated macrophages, myeloid-derived suppressor cells and T regulatory cells, but decreased CD8+ T cells in gastric tissues." (PMID 37572185, 2023). "CCL20, the major member of the C-C chemokine ligand family, was more abundant in the UM with tumor-infiltrating lymphocytes, which is associated with poor prognosis." (PMID 36769510, 2023). "Another retrospective clinical study revealed that the expression of CCL20 was significantly associated with tumor recurrence and survival outcomes in HCC patients." (PMID 37545521, 2023). "In patients with HCC, CXCL5 serum levels were associated with tumor progression, and levels of CCL20 and CXCL8 with macrovascular invasion." (PMID 36982370, 2023). "CCL20 can also be produced by tumor-associated macrophages in the tumor microenvironment of KIRC and then activate the cancer cells via Akt activation, followed by acquired migration activity and epithelial-mesenchymal transition." (PMID 37484803, 2023). "Previous studies have indicated that CCL20 secreted by tumor-associated macrophages (TAMs) activates the expression of CCR6 in tumor cells and then induces cell proliferation and migration, as well as epithelial–mesenchymal transition (EMT)." (PMID 35841069, 2022). "Some studies also indicate a significant role of chemokines (including CCL20) in the migration of Treg lymphocytes from neoplastic tissues, which reportedly fosters tumor progression as well as it being associated with poor HCC prognosis." (PMID 36012108, 2022). "It has also been shown that the concentration of CCL20 in this cancer is associated with tumor size, vascular invasion, tumor differentiation, risk of recurrence, and even survival rates of HCC patients." (PMID 35408440, 2022). "Multiple studies have shown that CCL20 is expressed in tumor cells and tumor-associated macrophages, which can activate CCR6 on cancer cells in an autocrine manner, causing their migration and epithelial-to-mesenchymal transitio n." (PMID 35065633, 2022).
tumor (continued). "Taken together, CCL20 is extensively associated with tumor immunity, cytokine activity, inflammation, and oncogenic signaling pathways in LUAD." (PMID 35864953, 2022). "High IL-37 expression by HCC tumor cells is associated with upregulated levels of CCL3 and CCL20 and increased recruitment of CD1a+ dendritic cells (DCs) in tumor infiltrations." (PMID 36551790, 2022). "The role of chemokines in EMT induction in epithelial tumor cells has been investigated, and the evidence has implicated CCL20 in such processes." (PMID 34569432, 2021). "CCL20-encoded proteins are capable of chemotaxis of lymphocytes, allowing the tumor to form an immune tolerance state." (PMID 34881236, 2021). "We next aimed at unravelling the underlying mechanism of tumour-derived CCL20 promotion of tumour progression, growth and poor prognosis." (PMID 32601464, 2020). "The effects of CCL20 on endothelial cell migration and tumour-associated vascularisation were comprehensively analysed with chemotaxis assays in vitro and in CCR6-deficient mice in vivo." (PMID 32601464, 2020). "High CCL20 expression in the tumor stroma is determined to be a poor prognostic factor, while CCL20 mRNA expression of TAM is higher than that of tumor cells, cancer-associated fibroblasts, T cells, and peripheral blood monocytes within tumor tissues." (PMID 32707869, 2020). "CCL20 expression was positively associated with FOXP3 expression in tumor tissues as analyzed by immunohistochemistry." (PMID 31395078, 2019). "CCL20-producing tumor associated macrophages were associated with tumor progression and worse survival possibly because they co-expressed pro-tumor cytokine TNF and pro-angiogenic VEGF-A." (PMID 30899263, 2019). "Here, important chemoattractants such as Ccl20 and Ccl5 were downregulated in the microarray of IL-6Rα-deficient tumours." (PMID 29695802, 2018). "CCL-20/macrophage inflammatory protein-3α derives from macrophages in numerous types of tumours, which causes the recruitment of CCR-6-expressing lymphocytes." (PMID 29695802, 2018). "First, CCL20 had markedly elevated expression in tumor tissue and strongly associated with the prevalence of Th17 cells in the same microenvironment." (PMID 25768730, 2015). "One study reported that tumor-associated macrophages recruit CCR6+ regulatory T cells to tumor mass and promote its development via enhancing the production of CCL20 in a CRC mouse model." (PMID 24559209, 2014). "The logistic regression analysis revealed that a high IHC score for CCL20 expression in the rectal mucosa and a disease duration of more than eight years were significantly correlated with the development of UC-associated neoplasia (P<0.05)." (PMID 24179507, 2013). "In the logistic regression analysis, the duration of the disease (>8 years) and the IHC scores of CCL20 above the cut-off value were significantly associated with the development of UC-associated neoplasia (P=0.0287)." (PMID 24179507, 2013). "In the PCA tissues we observed CCL20 immunoreactivity in the cytoplasms of ductal epithelial cancer cells, in infiltrates of perineural sheaths and also in tumor-associated macrophages." (PMID 20459729, 2010). "Furthermore, the observed correlation between Fusobacterium abundance and CCL20 expression suggests that microbial modulation of tumor-associated gene expression plays a role in OSCC development." (PMID 40869423, 2025). "CCL20 is associated with lipid droplet accumulation-mediated macrophage survival and regulatory T cell (Treg) recruitment, indicating its potential role in lipid metabolism in the tumor microenvironment." (PMID 40070829, 2025).
tumor (continued). "This analysis revealed a positive correlation between CCL20 and GLI1 expressions (r = 0.39, p < 0.01) via Spearman correlation, suggesting that GLI1 and CCL20 may be functionally linked in HCC tumours." (PMID 40913253, 2025). "Furthermore, both IL6 and CCL20 are implicated in promoting monocyte migration, a key factor in the inflammatory tumour environment." (PMID 40913253, 2025). "We hypothesized that interference with Cxcl3 and Ccl20 may cause differences in T-cell immune function, which may influence tumor formation." (PMID 40179015, 2025). "In addition, it has been reported that among the immunosuppressive effect, CCL20 causes tumor progression by promoting crucial cellular processes including proliferation, invasion, angiogenesis and chemoresistance in several tumor entities." (PMID 38730689, 2024). "The strong association with other oncogenic stimuli could enhance tumor growth in high-CCL20 tumors and patients." (PMID 38730689, 2024). "Consequently, a high serum CCL20 concentration before therapy is an independent risk factor for tumor progression." (PMID 38730689, 2024). "Previous studies reported that the CCL20 expression level in tumor tissues is associated with clinical prognosis in multiple cancer types 12, but its prognosis value in LUAD is unknown." (PMID 35864953, 2022). "However, emerging evidence strongly suggests association between CCL20 and tumor progression in several solid tumors." (PMID 34569432, 2021). "However, only one small study with 11 HCC patients reports a significant association between CCL20 expression and tumor grading (TNM stage 3 vs. 2)." (PMID 34638361, 2021). "Among them, a link between CCL20 and tumor-associated macrophages (TAMs) has been established." (PMID 34569432, 2021). "Importantly, several established roles, including tumor growth, inhibition of apoptosis, angiogenesis and therapeutic resistance have been linked to the expression of CCL20 in the tumor microenvironment." (PMID 34569432, 2021). "In conclusion, we have shown that serum CCL20 is closely associated with tumor progression and might serve as diagnostic and prognostic biomarker for PC." (PMID 33123272, 2020). "Hence, Fusobacteria and Prevotella can trigger CCL20 release through tumor cells in vitro, while Th17 infiltration in vivo was associated with “cold” (poor in tumor infiltrating lymphocytes) CRC." (PMID 33381121, 2020). "CCL20 is a component of the complex regulation of tumour-associated angiogenesis, and therefore its receptor CCR6 might represent a promising target for anticancer therapy." (PMID 32601464, 2020). "Our analysis of possible targets for CCL20 action within the tumour microenvironment implicated microvascular endothelial cells due to their high expression of CCR6 on their cell surface in vitro, and due to the observation of CD31+/CCR6+ vessels closely apposed to tumour tissue of patients." (PMID 32601464, 2020). "In addition to recruiting cells to a tumor niche, CCL20 increases cancer cell proliferation, causes cancer cell migration and invasion, and induces EMT of cancer cells." (PMID 33076281, 2020). "Higher expression of CCL20 and IL-17A together or respectively were significantly associated with higher T stage, N stage, M stage, overall stage, deep invasion, liver metastasis, larger tumor size, adenocarcinoma type, and CEA values." (PMID 31387598, 2019). "However, although expression of Ccl5 and its receptors Ccr1 and Ccr3 were not affected by IL-6Rα deficiency in CAC, expression levels of Ccl20 and of its unique receptor Ccr6 were reduced in knockout tumours." (PMID 29695802, 2018). "This infiltration might be in part due to the presence of high concentrations of CCL20, often detected within these primary tumor lesions and mainly produced by tumor-associated macrophages." (PMID 30420855, 2018).
tumor (continued). "The results suggest that an evaluation of CCL20 expression in the rectal mucosa may be useful to identify patients who are at a high risk for developing UC-associated neoplasia in adult." (PMID 25691899, 2015). "In conclusion, the results of the present study suggested that an evaluation of CCL20/CCR6 expression in the rectal mucosa may be useful for the identification of high-risk patients with UC-associated neoplasia." (PMID 24179507, 2013). "The results suggest that an evaluation of CCL20 expression in the rectal mucosa may be useful to identify patients who are at a high risk for developing UC-associated neoplasia." (PMID 24179507, 2013). "Gut TH17 seems to be a potential source for tumor-associated TH17, where it could be homed to the tumor environment via CCR6/CCL20 axis and expand locally." (PMID 23316374, 2012). "Moreover, in certain malignancies, heightened CCL20 expression may be associated with tumor invasion and metastasis." (PMID 39228662, 2024). "Therefore, TAMs with a low CM ratio may promote tumor progression and immune suppression by upregulating CCL20 and CCL2, which is a potential cause of poor patient prognosis." (PMID 39776914, 2024). "Therefore, in addition to its potential role in the recruitment of tumor infiltrating lymphocytes or tumor-associated immature DCs, CCL20 may also contribute to tumor cell growth and migration via autocrine and paracrine mechanisms." (PMID 24979261, 2014). "CXCL10 promotes anti-tumor immunity by chemotactically attracting effector immune cells, while CCL20 likely recruits Tregs, inhibiting the function of effector immune cells." (PMID 41399390, 2026). "In vivo neutralization of CCL20 resulted in reduced tumor volume, prolonged survival, and decreased M-MDSCs, thus affirming the role of CCL20 in mediating immunosuppression." (PMID 41688273, 2026). "When tumor cells highly expressed CXCL10 but lowly expressed CCL20, there was a significant infiltration of CD8+ T cells and CD20+B cells, but no Treg cell infiltration." (PMID 41399390, 2026). "In a cohort of 109 primary NPC samples, we observed that when tumor cells highly expressed CCL20, there was a significant infiltration of Treg cells." (PMID 41399390, 2026). "We next analyzed tumor-infiltrating Tregs in immunoreconstituted mice bearing CCL20-overexpressing 5-8F xenografts, using input human PBMCs from the immunoreconstitution procedure as controls." (PMID 41399390, 2026). "The tumor cells were further subgroup into tumor high and tumor low utilizing the GLMscore formula, the SPP1+ and CCL20+ macrophages shared elevated intercellular communications with tumor high cells." (PMID 40443528, 2025). "In NSCLC, CCL20 activated through STAT3 signaling impaired the sensitivity of tumor-bearing mice to crizotinib via VEGFA/IL6-mediated angiogenesis." (PMID 39985603, 2025). "Accumulating studies have shown that CCL20-mediated interaction between tumor cells and macrophages influences several tumor processes including metastasis, immunosuppression, angiogenesis, and proliferation." (PMID 39985603, 2025). "An EPS from lactobacilli strains has been reported to increase CCR6+ CD8+ T-cell populations in Peyer’s patches, supporting their migration to CCL20-expressing tumor sites and thereby boosting the effects of immune checkpoint blockades (e.g., anti-CTLA-4 mAb)." (PMID 41301527, 2025). "This overexpression of VDR in PC cells promotes the recruitment and polarization of macrophages into M2 macrophage phenotype via the secretion of CCL20, which leads to the activation of tumor progression." (PMID 41009006, 2025). "Here, we identify NSCLC-specific overexpression of the CXCL13 and CCL20 chemokines within the tumor microenvironment (TME) and develop a dual chemokine receptor strategy to overcome this barrier." (PMID 40764989, 2025).
tumor (continued). "This bacterium suppresses miR-1322 via the NF-κB signaling pathway, increasing the expression of CCL20, promoting immune cell infiltration, and polarizing macrophages toward a pro-tumor phenotype." (PMID 39973938, 2025). "In in vitro models, they demonstrated that radiation-induced tumor cell–derived microparticles (RT-MPs) containing double-stranded DNA (dsDNA) upregulated the cGAS/STING/NF-κB pathway in macrophages to stimulate CCL20 production." (PMID 41392975, 2025). "Th17 cells can be recruited to the tumor sites by the expression of CCR6 and binding to its natural ligand CCL20 highly expressed on tumor tissues, which is coordinated by long non-coding RNA (lncRNA-u50535)." (PMID 40963621, 2025). "Using conditioned medium (CM) from 10 Gy–irradiated tumor cells, we observed considerable upregulation of Ccl20 expression in macrophages compared with control CM." (PMID 41055972, 2025). "C-C Motif Chemokine Ligand 20 (CCL20), a key mediator in the tumor microenvironment, was also significantly upregulated in OSCC saliva, with even higher levels in advanced-stage cases (p = 0.004)." (PMID 40869423, 2025). "While CCL20 has tumor-promoting functions, it also recruits dendritic cells and elicits antitumor immune responses under certain condition, indicating a context-dependent dual role." (PMID 41459506, 2025). "In immunocompetent HCC tumor-bearing mice, CCL20 neutralization not only suppressed tumor metastasis but also inhibited angiogenesis." (PMID 39985603, 2025). "Following expansion in Peyer’s patches, these cells migrate to the TME that expresses the cognate chemokine CCL20, where they directly enhance anti-tumor activity." (PMID 41403943, 2025). "In inflammatory breast cancer, EGFR regulates the expression of key chemokines including CCL20 to promote tumor progression by increasing the infiltration of Tregs while decreasing CD8 + T cells." (PMID 39985603, 2025). "CCL20 is a chemokine that can interact with multiple cytokines and Toll-like receptors, resulting in increased tumor aggression." (PMID 40179015, 2025). "Our findings demonstrated that tumor growth was accelerated in the Sh‐vector+CCL20 group, whereas it was decelerated in the Sh‐CXCL5+PBS and Sh‐CXCL5+CCL20 groups." (PMID 40091357, 2025). "Radiated tumor cell–released RT-MPs leads to Ccl20 upregulation in macrophages via cGAS-STING/NF-κB signaling pathway." (PMID 41055972, 2025). "CCL20, also known as intestinal epithelial chemoattractin (MIP-3α), is a chemokine that promotes tumor development and represents a potential therapeutic target." (PMID 41417784, 2025). "CCL20 can promote direct tumor growth, epithelial-mesenchymal transition, angiogenesis, and immunosuppression of CD8+ T cells." (PMID 40114916, 2025). "Autocrine CXCL5 regulates tumor stemness, while its paracrine action recruits THP‐1‐Mφ and promotes M2 polarization, thus underscoring the critical role of the CCL20/CXCL5 axis in the progressive tumor microenvironment." (PMID 40091357, 2025). "CCL20, a specific chemokine regulated by miRNA-1322, is crucial for tumor metastasis and progression." (PMID 39921821, 2025). "Although CCL20 exerts antitumor effects, CCL20 produced by tumor cells or immune cells can also create an immunosuppressive tumor microenvironment to support tumor progression." (PMID 39985603, 2025). "High-risk genes (TNF, CXCL1, CCL20, ITGA5, CXCL3) typically promote tumor progression and immune evasion by inducing the expression of chemokines or modulating cellular responses to chemokines." (PMID 40517358, 2025). "Blocking CCL20 has been found to inhibit angiogenesis, demonstrating its role in tumour vascular development." (PMID 40913253, 2025). "In treatment-naive samples, Mono_EREG exhibited high expression of CCL family genes (CCL3L3, CCL20), EREG, and BCL2A1, which are associated with tumor progression, suggesting functional impairment." (PMID 40725006, 2025).